HPN (hepsin)
Diseases named in the same sentence as HPN in open-access papers (continued):
Sharing a sentence is not in itself a finding about the gene and the disease.
tumor (continued). "In patients with metastatic CRC at diagnosis, the relationship of HPN with tumor histological grade and metastatic spread supported “the HPN paradox”, according to which tumors have developed a precise spatiotemporal restriction of HPN overexpression." (PMID 35804878, 2022). "Thus, in ovarian cancer, HPN contributes to tumor progression, whereas in endometrial cancer, it inhibits tumor cell growth." (PMID 35804878, 2022). "HPN staining in the primary tumor was not substantially associated with PFS or OS nor with thrombotic risk." (PMID 35804878, 2022). "Moreover, the radioligand uptake in 22Rv1 tumors increased over time, whereas the uptake in PC3 tumors decreased, suggesting that tumor uptake was due to the specific binding of [64Cu]3B to hepsin." (PMID 36145330, 2022). "Moreover, HPN is a potential independent prognostic biomarker for HCC and is strongly associated with clinicopathological features, tumor-infiltrating status of immune cells both in our discovery cohort and database surveys." (PMID 35164791, 2022). "Consequently, this assumption was further tested by investigating the correlation between HPN expression and tumor-infiltrating immune cell subtypes in HCC patients in the TIMER database." (PMID 35164791, 2022). "Therefore, hepsin is a critical protease for Ras-dependent tumorigenesis and early tumor dissemination." (PMID 35204704, 2022). "Here, by comparing isogenic transfectants of the PCa cell line PC-3 providing inducible overexpression of wild-type hepsin (HPN) vs. the protease-deficient mutant HPNS353A, we were able to attribute hepsin-mediated tumor-adverse effects to its excess proteolytic activity." (PMID 31399560, 2019). "In addition, levels of hepsin protein correlated positively with C3 expression in human non-tumor liver tissues." (PMID 26760961, 2016). "Taken together, these studies indicate that the mislocalization and overexpression of hepsin could potentially initiate basement membrane degradation and lead to tumor cell invasion." (PMID 26014348, 2015). "Analysis of testisin, hepsin, and matriptase mRNA expression in the tumor cell lines susceptible to PrAg-PCIS toxin revealed that the tumor cell lines expressed variable levels of some or all of the three proteases, providing the means for PrAg-PCIS activation." (PMID 26392335, 2015). "As hepsin, and multiple other membrane-anchored serine proteases have been found to be overexpressed in multiple tumor types, this may be an unexpected beneficial feature of PrAg-PCIS." (PMID 26392335, 2015). "Notably, since matriptase and hepsin have identical substrates and since both have possible tumor progression and metastasis-promoting activities, further studies of TMPRSS3 are needed to better understand its functions and substrates." (PMID 26014348, 2015). "The activation of PrAg-PCIS toxin by testisin and hepsin expressed by tumor cells in cell culture reflected the cleavage of PrAg-PCIS in vitro, yet matriptase was ineffective at activating PrAg-PCIS toxin when expressed as a full-length protein on the cell surface." (PMID 26392335, 2015). "This hypothesis suggested that in the initial stages of metastasis, hepsin overexpression might stimulate the invasion of primary tumor cells but, once the cells metastasized, hepsin expression would no longer be essential in distant lesions." (PMID 26014348, 2015). "Thus, hepsin can multiply and increase proteolysis on the surface of tumor and stromal cells, which aggravates the damage to the basal membrane and accelerates tumor progress." (PMID 22649671, 2011). "This hypothesis confirms the data on the suppression of the tumor cell’s invasive growth when hepsin activity is inhibited." (PMID 22649671, 2011). "Hepsin mediates the digestion of extracellular matrix components in initial tumor growth." (PMID 20825641, 2010).
tumor (continued). "Indeed, hepsin could efficiently activate pro-uPA and then initiate plasmin-mediated proteolytic pathways at the tumor–stroma interface, leading to basement-membrane disruption and tumor progression." (PMID 35204704, 2022). "Analysis of the relationship between HPN expression and histological grade of tumor differentiation reflects that globally, there is an increase in HPN expression from well-differentiated to moderately differentiated tumors, which is particularly evident in the case of advanced neoplasms." (PMID 35804878, 2022). "Furthermore, our study offers insights for further studies on tumor immunotherapy based on the potential that HPN may affect the prognosis of HCC through tumor immune infiltration." (PMID 35164791, 2022). "Thus, because of the high specificity of hepsin expression in tumor cells, there is an opportunity to answer the question as to whether the neoplasm in prostate is benign or malignant." (PMID 22649671, 2011). "Our findings provide a new potential mechanism by which HPN may play an important role in the susceptibility of rs10954732 A allele carriers to HCC and their prognosis through tumor immune infiltration, thus offering potential insights for future studies on tumor immunotherapy." (PMID 35164791, 2022). "The trypsin-like serine proteases, matriptase, hepsin and HGF activator (HGFA), which are commonly over-expressed in tumor cells, are three principal proteases responsible for HGF activation." (PMID 28420162, 2017). "The activity of matriptase, HGFA and hepsin is controlled by the endogenous inhibitors of pro-HGF activation, the HGFA inhibitors (HAI)-1/2, whose expression is reduced in tumor tissues." (PMID 28420162, 2017). "We confirmed that structurally distinct triplex inhibitors of matriptase, hepsin and HGFA block the crosstalk between tumor cells and fibroblasts." (PMID 27121052, 2016). "As the expression of hepsin was very low in HCC tissues, correlation analysis based on immunohistochemical staining was studied in 30 non-tumor liver tissues." (PMID 26760961, 2016). "Further, low expression levels of TMPRSS1 and TMPRSS3 mRNA and hepsin and TMPRSS3 predict advanced tumor malignancy and poorer prognosis." (PMID 26014348, 2015). "Similarly, the expression of hPn-ASVs with exon 21 mRNA was also increased in tumor tissue, as compared to NAT, in a similar manner as total hPn." (PMID 39334860, 2024). "Moreover, when the hepsin transgenic mice were cross-mated with the LPB-Tag 12T-7f models, the bi-transgenic mice showed significant tumor progression and metastases to the bone." (PMID 35204704, 2022). "The results indicate that HPN expression was in strongly negative correlation with 35 marker genes of infiltrating immune cells regardless of whether the correlation analysis was adjusted for purity or not, such as tumor-associated macrophages (TAM), M2 macrophages, monocytes, and neutrophils." (PMID 35164791, 2022). "Furthermore, the tumor volume of the mice that received the multiantigen vaccine was significantly lower compared to the mice receiving the AMACR (p < 0.0001), HPN (p = 0.019) or the PSMA (p = 0.002) single antigen vaccines." (PMID 35948756, 2022). "We do not know the mechanism by which HPN maintains this effect when the tumor is removed, and future studies will be necessary to understand this association." (PMID 35804878, 2022). "Instead, overexpression of wild-type hepsin, but not of HPNS353A, induced relocalization of the protein to the cytoplasm, and increased autophagic flux in vitro as well as LC3B punctae frequency in tumor xenografts." (PMID 31399560, 2019).
adenocarcinoma (2 papers, 2014 to 2022). A common cancer characterized by the presence of malignant glandular cells. "Further studies showed that hepsin/myc bigenic mice generated by crossing PB-hepsin mice with the PB-Hi-myc transgenic mouse model developed invasive adenocarcinoma at 4.5 months and higher-grade adenocarcinoma at 12–17 months of age." (PMID 35204704, 2022). "LPB-Tag/PB-Hepsin mice are derived from LPB-Tag animals (12T-7f adenocarcinoma line), which express SV40 large T antigen, but do not express Hepsin." (PMID 24657880, 2014).
HPN also shares sentences with these, for which no sentence is quoted: breast tumor (2 papers); Hyperglycemia (2); hyperlipidemia (2); adenoid cystic carcinoma (1); benign breast tumor (1); cholestasis (1); chronic pancreatitis (1); colon cancer (1); colorectal tumors (1); dysplasia (1); endocarditis (1); endometrial cancer (1); glioblastoma (1); Hypertension (1); invasive breast carcinoma (1); lung squamous cell carcinoma (1); metastatic colorectal cancer (1); metastatic prostate carcinoma (1); metastatic tumors (1); mood disorder (1); ovarian serous adenocarcinoma (1); ovarian tumor (1); pancreatic cancer (1); periodontitis (1); preeclampsia (1); reproductive system disease (1); Respiratory tract infection (1); Sepsis (1); thromboembolic diseases (1); virus infections (1).